CD40 (CD40 molecule)
Diseases named in the same sentence as CD40 in open-access papers (continued):
Sharing a sentence is not in itself a finding about the gene and the disease.
lupus (continued). "Blockade of the CD154/CD40 interaction inhibited T-cell-dependent B-cell proliferation, differentiation, and antibody formation in in-vitro studies and in lupus mouse models." (PMID 28793932, 2017). "At present, CD40 rs4810485 is one of the most studied gene polymorphisms that is closely related to the susceptibility to rheumatoid arthritis (RA) and systemic lupus erythematosus (SLE)." (PMID 28320398, 2017). "In agreement with previous studies, the expression of CD80, CD86, and CD40 after culture with LPS was diminished in moDC from lupus patients compared with healthy controls." (PMID 27057555, 2016). "Since pDCs are essential for lupus like disease development in mice, we next examined the expression of CD40 and CD80 on the surface of pDCs following stimulation with TLR9 agonist (CpG)." (PMID 27232337, 2016). "CD40 silencing reduced the glomerular deposits of IgG and C3 in these mice, revealing a possible role of LPS-TLR4-CD40 signaling in the pathogenesis of lupus." (PMID 26648937, 2015). "Transfer of CD40-activated T2-MZP Bregs inhibited the development of lupus in recipient mice via the induction of IL-10-producing Tregs." (PMID 26071023, 2015). "CD40L, which is overexpressed on lupus T cells, stimulates CD40 expressed on B cells to produce autoantibodies." (PMID 24864268, 2014). "To compare the effect of T-cell activated DCs on B cells between lupus-prone TC and B6 mice, we used co-cultures of anti-CD40 activated BMDCs from either strain and B6 B cells." (PMID 25093822, 2014). "Our group has shown lupus patients have an increased expression of co-stimulatory molecules such as CD40 and CD86, suggesting that DCs immunogenicity is augmented." (PMID 25229821, 2014). "Our results show that anti-CD40 activated BMDCs from TC lupus-prone mice induce a greater B cell proliferation in an IL-6 and IFN-γ dependent manner." (PMID 25093822, 2014). "In our study we confirmed the presence of plasma cell within the renal interstitium of lupus non treated mice; their presence was diminished in siRNA CD40 treated groups." (PMID 23799000, 2013). "In B cells from lupus patients, NF-κB activation was mainly via CD40, and it depended both on IκB phosphorylation and proteosome degradation." (PMID 22952582, 2012). "Inhibition of proteosome degradation with LAC and IκB phosphorylation with BAY were similarly effective in blocking CD40-induced NF-κB signaling in B cells from lupus patients and normal controls." (PMID 22952582, 2012). "CD40-induced NF-κB activity was blocked by both IκB phosphorylation and proteosome degradation inhibitors in both lupus and normal B cells." (PMID 22952582, 2012). "CD40 induced NF-κB activation is different in human lupus B lymphocytes compared with normal B cells." (PMID 22952582, 2012). "CD154 is expressed at relatively high levels by both T cells and B cells in SLE patients and in a mouse model of lupus, which is proposed to drive CD40 signaling, B cell hyperactivity, and autoAb production." (PMID 21799861, 2011). "Aberrant CD40 ligand (CD154) expression occurs on both T cells and B cells in human lupus patients, which is suggested to enhance B cell CD40 signaling and play a role in disease pathogenesis." (PMID 21799861, 2011). "We therefore propose that the marked effects of the blockade of CD40L in patients and murine model of lupus are also due to the inhibition of CD40 triggering on DCs." (PMID 16507174, 2006). "Whereas the alteration in CD80/CD86 ratio is evident only after the onset of the disease, the overexpression of CD40 precedes the onset of lupus and is sustained even during the course of the disease." (PMID 16507174, 2006). "We therefore asked which DC subset is responsible for the increase in CD40-positive DCs in lupus-prone mice." (PMID 16507174, 2006). "We found that lupus BM-DCs expressed levels of CD40 comparable to those of BALB/c and B6 BM-DCs in terms of both percentage of positivity and MFI." (PMID 16507174, 2006).
lupus (continued). "Lupus DCs showed an altered ex vivo costimulatory profile, with a significant increase in the expression of CD40, decreased expression of CD80 and CD54, and normal expression of CD86." (PMID 16507174, 2006). "Similarly, genetically engineered cellular nanovesicles bearing CD40 were found to effectively inhibit the immune response in mouse models of systemic lupus erythematosus and especially deliver a mycophenolate load by achieving an enhanced outcome." (PMID 40643538, 2025). "In spite of promising results obtained with the anti-CD40 Ab treatment, its effect was abrogated upon treatment cessation, unlike the long-lasting effect exhibited by the anti-CD154 Abs in lupus-prone mice, underlining the possible induction of tolerance in the latter case." (PMID 39404385, 2024). "Interestingly, the same study demonstrated the efficiency of anti-CD40 in reducing inflammation in yet another model of spontaneous lupus, the MRL/lpr mouse." (PMID 39404385, 2024). "Furthermore, murine MAIT cells promote B-cell autoantibody production in vitro in a mouse model of lupus via CD40L:CD40 signaling." (PMID 36072570, 2022). "Based on our data presented here, it is reasonable to hypothesize that in the B6.Nba2 lupus-like model IFNαβ may be increasing B cell activation, leading to increases in CD40+ B cells." (PMID 33488628, 2020). "Here we analyzed the B cell regulation of Th17/Th22 cell differentiation in lupus and found that α-IgM- and α-CD40-activated B cells could inhibit Th17 and promote Th22 cell differentiation from naive T cells under Th17 cell culture conditions." (PMID 32127533, 2020). "Furthermore, estrogens stimulate calcineurin expression which enhances expression of the X-linked gene product CD40L on lupus CD4+ T cells, resulting in their strengthened crosstalk with CD40-expressing B cells and autoantibody production in SLE patients." (PMID 31575058, 2019). "In addition, high expression of CD40L detected on lupus T cells was responsible for excessive stimulation of CD40 expressed on B cells." (PMID 29854836, 2018). "Its expression increases by Toll-like receptor 7 (TLR7) stimuli in plasmacytoid DCs from New Zealand Black/White F1 hybrid (NZB/W F1) mice with symptomatic lupus, leading to the expression of the CD40 co-stimulatory molecule required to facilitate the T cell activation." (PMID 30322050, 2018). "The discrepancy may have been due to different lupus-prone mouse models used or different activation methods (anti-CD40 versus LPS), although another study has shown that LPS could increase IL-6 production from BMDC of B6.Sle1.Sle2.Sle3 mice." (PMID 27034965, 2016). "Overall, our findings suggest that the elevated miR-155 induction may contribute to the enhanced TLR7-induced CD40 expression in pDCs derived from BM of lupus mice." (PMID 27509492, 2016). "Moreover, we found the activities of the upstream kinases in CD40/NF-κB signaling in B cells from lupus patients were also different from that in normal controls, but mimicked that of tonsil B cells." (PMID 22952582, 2012). "Next we investigated if CD40 stimulation could induce further activation of NF-κB signaling in B cells from lupus patients." (PMID 22952582, 2012). "Although the cell surface expression of CD40 in B cells from lupus patients was similar to normal controls, which was in consistent with previous study, our study, however, revealed that CD40 expression was reduced in raft portion in B cells from lupus patients." (PMID 22952582, 2012). "CD40 induced NF-κB activation is different in lupus B lymphocytes compared with normal B cells." (PMID 22952582, 2012). "Furthermore, splenic DCs from mice with lupus showed a normal upregulation of CD40 expression on activation in vitro." (PMID 16507174, 2006). "To determine whether lupus DCs have a normal capacity to upregulate CD40 expression after activation, we used the traditional protocol by Inaba and colleagues to isolate splenic DCs." (PMID 16507174, 2006).
lupus (continued). "The aim of this study was to investigate the characteristics of CD4+CD40+ T cells (Th40 cells) in Chinese systemic lupus erythematosus (SLE) patients." (PMID 37400575, 2023). "NF-κB-inducing kinase (NIK) mediates non-canonical NF-κB signaling downstream of multiple TNF family members, including BAFF, TWEAK, CD40, and OX40, which are implicated in the pathogenesis of systemic lupus erythematosus (SLE)." (PMID 29330524, 2018). "According to literature, CD40 engagement contributes to activation of NF-κB signaling in B cells, it would be interesting to see whether in B cells from lupus patients, the constitutive activation of NF-κB pathway was induced in association with CD40 signaling." (PMID 22952582, 2012). "Auto-reactive B lymphocytes and its abnormal CD40 signaling play important roles in the pathogenesis of systemic lupus erythematosus (SLE)." (PMID 22952582, 2012). "Additionally, we detected decreased levels of CD54, and a specific increase in CD40 on lupus DCs." (PMID 16507174, 2006). "The increase in CD40 may instead participate in disease pathogenesis, being present months before any sign of autoimmunity, and its downregulation should be explored as an alternative to treatment with anti-CD40 ligand in lupus." (PMID 16507174, 2006). "Given the pivotal role of aberrant T–B cell crosstalk in systemic lupus erythematosus (SLE), CD40 blockade represents a promising therapeutic approach." (PMID 41373894, 2025). "Decreased MHCII, CD40, TNF-α, C2, and C7 in the systemic lupus erythematosus signaling pathway further downregulate MAC expression and reduces tissue damage and inflammatory response." (PMID 36245510, 2022). "The expression of a chimeric molecule with the mouse CD40 extracellular domain and the LMP1 intracellular signaling regions in lupus-prone mouse strain accentuated the autoimmune phenotype." (PMID 33613559, 2020). "In lupus-prone MRL/Lpr mice, successive administration of anti-CD40 antibodies remarkably induced the expansion of IL-10-secreting transitional B cells, along with ameliorated lupus nephritis development." (PMID 31795353, 2019). "KEGG analysis revealed the systemic lupus erythematosus pathway involving CD86, TNF, C4, FCGR2B, CD80, C3, CD40, and C1S." (PMID 28976997, 2017). "A couple of them have shown that GM-CSF/IL-4-induced BMDC from B6.Sle1.Sle2.Sle3 lupus-prone mice, compared to BMDC from B6 mice, promoted better B cells proliferation and IgM/IgG production in in vitro coculture system upon anti-CD40 ligation." (PMID 27034965, 2016). "cDC in the blood of SLE patients or secondary immune tissues of lupus-prone mice have been shown to exhibit elevated expression of CD40, CD80, CD86, PD-L1, and PD-L2, suggesting that cDC in lupus may be activated and immunogenic." (PMID 27034965, 2016). "Activation of CD40 signaling is present in type 1 diabetes, multiple sclerosis (MS), inflammatory bowel disease (IBD), psoriasis, rheumatoid arthritis, and systemic lupus erythematosus (SLE)." (PMID 26809818, 2016). "The response of cultured DC from lupus mice and normal mice to MVs from 4-NQO-treated 32Dcl3 cells revealed induction of CD40 that was significantly higher in MRL/lpr DC using 50 μg/ml MVs, while it was comparable with normal mice using 100 μg/ml MVs or LPS." (PMID 25886192, 2015). "All together, our findings revealed that canonical NF-κB signaling is constitutively activated in active lupus and is mediated by CD154/CD40." (PMID 22952582, 2012). "The relative band density of CD40 in raft from B cells in normal controls and lupus patients were 1.0±0.39 vs. 0.41±0.28, p<0.05, suggesting CD40 underwent degradation in raft portion in peripheral B cells from active SLE patients." (PMID 22952582, 2012). "Taken together, our study demonstrated NF-κB signaling is constitutively activated in active lupus and is mediated by CD154/CD40." (PMID 22952582, 2012).
lupus (continued). "We next tested the expression of CD40 in cell surface as well as in soluble portion, high density insoluble portion (HDI) and raft portion in lupus and normal B cells." (PMID 22952582, 2012). "In the 3 lupus patients studied, MDDCs responded to LPS stimulation with increased expression of HLA-DRII, CD40, and CD86." (PMID 20169063, 2010). "DCs from young lupus-prone NZM2410 mice, before the development of the disease, expressed normal levels of CD80 and CD86 but already overexpressed CD40." (PMID 16507174, 2006). "We also examine how dysregulated CD40/CD40L signaling contributes to key pathological features of Rheumatoid arthritis, Systemic lupus erythematosus, and Sjögren's syndrome, including ectopic germinal center reactions, pathogenic autoantibody production, and chronic tissue inflammation." (PMID 42233036, 2026). "CD40 expression is greatly upregulated in proliferative lupus nephritis, and several studies have demonstrated hyperexpression of CD40L by T cells and increased soluble CD40L (sCD40L) concentrations in lupus patients." (PMID 40332536, 2025). "Studies on cynomolgus and rhesus monkeys with lupus demonstrated that treatment with CFZ533 induced a complete suppression of germinal center development in lymphoid organs, highlighting its capacity to inhibit CD154/CD40-induced pathways." (PMID 39404385, 2024). "We identified a novel regulation of CD40 expression by miR-155, by which may contribute to the hyperactivated TLR7 response in lupus pDCs." (PMID 27509492, 2016). "Interestingly, DCs from lupus patients show higher expression of co-stimulatory molecules, such as CD86 and CD40, than DCs from healthy controls suggesting an immunogenic prone state for these cells." (PMID 25229821, 2014). "Whereas, so far, there is no data on raft expression of CD40, especially in B cells from lupus patients." (PMID 22952582, 2012). "The interaction of CD40 and CD154 have been shown to play a role in various diseases such as autoimmune thyroiditis, type 1 diabetes, inflammatory bowel disease, psoriasis, multiple sclerosis, rheumatoid arthritis, and systemic lupus erythematosus." (PMID 21976957, 2011). "Knowing that γδ T cells express CD40, an important co-stimulation might also occur via CD40L(CD154), which is expressed in a sustained manner at the surface of lupus CD4+ T cells and B cells." (PMID 19390596, 2009). "Nevertheless, we observed a slightly but significantly higher percentage of CD40-positive cells in CD8α+ DCs from lupus-prone mice than in non-autoimmune mice at a young age." (PMID 16507174, 2006). "Analysis of the literature suggests that the overexpression of CD40 and CD40L may be independent phenomena and may both be required for full lupus development." (PMID 16507174, 2006). "We found that in lupus-prone mice, after the onset of the disease, DCs expressed an abnormal state of activation with decreased levels of CD80 and CD54, normal levels of CD86, and a specific increase in cells expressing CD40." (PMID 16507174, 2006). "The levels of CD40 positivity in DCs of the two non-autoimmune strains were significantly different, but they were both much lower than in lupus DCs." (PMID 16507174, 2006). "We have found that resting lupus BM-DCs, differentiated in the artificial environment of culture in vitro, did not express increased levels of CD40." (PMID 16507174, 2006). "Stable expression of CD40 protein on cytomembrane vesicles can target CD4+ T cells and inhibit B cell proliferation to treat systemic lupus erythematosus (SLE) through CD40/CD40L interaction blockade." (PMID 40395752, 2025). "Furthermore, in the spontaneous lupus model, BXBS mice, B cells ectopically expressing CD154 showed increased proliferation which could be halted by the administration of anti-CD40 Abs." (PMID 39404385, 2024).
lupus (continued). "In this study, we analyzed CD40 expression and CD40/CD154 induced activation of NF-κB signaling pathway in B cells from SLE patients, and we demonstrated that canonical NF-κB signaling is constitutively activated in active lupus and is mediated by CD154/CD40." (PMID 22952582, 2012). "The increase in the percentage of CD40-positive DCs that we observed in NZM2410 and in NZB-W/F1 mice could be due to a pro-inflammatory environment present in lupus-prone mice even months before the onset of the disease, or to a primary alteration in the state of activation of DCs." (PMID 16507174, 2006). "The pDCs, which normally present a more immature phenotype than other subsets, expressed low levels of CD40 in all three strains, with normal percentages of CD40 positivity in young lupus-prone mice and increased percentages after lupus onset, although the increase was not statistically significant." (PMID 16507174, 2006). "Because the percentage of CD40-positive B cells in NZM2410 mice was significantly higher only in comparison with B6 but not with BALB/c mice, and this single difference was present only after onset of the disease, we propose that the overexpression of CD40 in lupus-prone mice is DC specific." (PMID 16507174, 2006). "The increase in IRF5 expression after activation with anti-IgM, anti-CD40, and R848 in vitro suggested the possibility that IRF5 might be increased in GC B cells in FcγRIIB−/−Yaa mice in vivo, because TLR7 activation is thought to be important for spontaneous GC formation in other lupus models." (PMID 34197340, 2021). "In addition, the reaction of B cells from lupus patients to anti-CD154 inhibition also mimicked that of tonsil B cells, which strongly suggested that B cells from lupus patients are in activated stage and CD40 plays similar role in activating NF-κB signaling in both SLE and tonsil B cells." (PMID 22952582, 2012). "This is in line with the previously reported finding that Btk is required for TLR-induced IL-10 production by B cells and that B cells from lupus-prone mice upregulate IL-10 production in response to TLR stimulation, but not to BCR or CD40 engagement." (PMID 30761150, 2019). "We found that lupus DCs from both NZM2410 mice and NZB-W/F1 mice upregulated CD40 to the same extent as the non-autoimmune DCs, therefore suggesting that the regulation of CD40 expression is not intrinsically altered." (PMID 16507174, 2006).